IL22 (interleukin 22)
Diseases named in the same sentence as IL22 in open-access papers (continued):
Sharing a sentence is not in itself a finding about the gene and the disease.
infection (continued). "However, the continued or robust expression of Th17 cytokines IL-17A and IL-22 during early infection is reliant on the presence of IL-23, which could be supplied by MAP-infected macrophages." (PMID 32258066, 2020). "Furthermore, evidence suggests that, following infection with T. trichiura, the human gut accumulates IL-22-producing Th cells within the intestinal mucosa and the resultant increase in IL-22 production and Th2 cytokines promotes goblet cell hyperplasia and mucus production." (PMID 33013869, 2020). "Moreover, upregulation of IL-22Ra1 may be an important mechanism to promote epithelial repair by allowing IL-22 to signal to cells that are undergoing infection, stress or injury." (PMID 31416461, 2019). "Hence IL-22 secreting cells at this site or IL-22+ cells migrating from this site into the gill would likely contribute to the local antimicrobial responses following infection." (PMID 31306696, 2019). "Moreover, the effect of IL-22 on anti-microbial production may be more relevant in responses to prokaryotic infections, such as those by C. rodentium." (PMID 30640950, 2019). "Moreover, the levels of EspF were significantly elevated in CR derived from the infected Il22-/- mice than those in the bacteria cultured in Luria–Bertani (LB) medium, hinting that EspF could play an important function during CR infection in vivo." (PMID 31251784, 2019). "Additionally, mouse intestinal mDC production of IL-23 in response to flagella derived from Salmonella was important in the stimulation of IL-22 from ILC3s and a need for physical contact between DCs and ILCs was necessary for the protective IL-22 response to infection with C. rodentium." (PMID 30984202, 2019). "In addition, IFN-γ and IL-22 were also significantly increased after H9N2 AIV infection." (PMID 29783653, 2018). "Collectively, the research done with both IL-22 and amphiregulin provides examples of the importance of host tolerance in maintaining barrier function in the lung and returning to homeostasis in order to promote survival following infection independent from resistance." (PMID 29988424, 2018). "IL‐22‐dependent fucosylation favours the occupancy of mutualistic species in intestinal niches close to the epithelial barrier and was shown to protect against infections by Salmonella spp., Citrobacter rodentium and the opportunistic pathogen Enterococcus faecalis." (PMID 27935637, 2017). "By stimulating early defense, IL-22 may actually prevent later infection." (PMID 28584821, 2017). "In addition, IL-22 induces the secretion of several antimicrobial proteins by epithelial cells such as the regenerating islet-derived proteins Reg3γ and Reg3β, thus limiting infection by extracellular pathogens." (PMID 27148267, 2016). "As we observed a temporary increased weight loss during the infection, we hypothesized that the acute immunopathology might be altered in the absence of IL-22." (PMID 27650379, 2016). "However, IL-22 KO animals lost less weight following infection." (PMID 27375092, 2016). "In addition, since our analyses during the natural history of SIV-infection were performed in the early chronic phase of infection (day 58 p.i.), we cannot determine how the function of IL-17 and IL-22 producing CD4+ T-cells are affected in the early acute infection." (PMID 26829644, 2016). "Conversely, IL-22 neutralization could ameliorate virus-induced inflammation in certain infections." (PMID 27303405, 2016). "Additionally, the production of IL-10 was increased in IL-22−/− mice upon infection." (PMID 27650379, 2016). "Nevertheless it remains unclear how IL-22 modulates the immune response during PbA infection." (PMID 27311945, 2016). "Moreover, following peroral infection of conventional adult mice with Arcobacter butzleri sharing taxonomic relationships to Campylobacterales, cytokines of the IL-23/IL-22/IL-18 axis were regulated not only in a strain and time course of infection, but also tissue dependent fashion." (PMID 27385977, 2016).
infection (continued). "Therefore, we asked if IL-22 regulated the lesion resolution in this infection as well." (PMID 26285207, 2015). "The increased expression of the IL22 gene observed in all segments of the small intestine of the inoculated lambs from the very first days of infection, could come from NK22/ILC22 cells (ILC3) and/or lymphoid tissue inducers (LTi) known to produce this cytokine in mice and humans." (PMID 25890354, 2015). "We first asked whether infection with leishmania parasites led to an increase in IL-22 production." (PMID 26285207, 2015). "Consequently, a consensus is beginning to emerge that IL-22 may exert antiviral control during infection." (PMID 24721575, 2014). "Local IL-22 within the lung could play a key role in host defence, epithelial repair and regeneration, and may be amenable to therapeutic intervention to promote healthy lung repair after damaging infection." (PMID 24587305, 2014). "Indeed, IL-22-producing NKp46+ cells expanded in infection in wild-type but not IL-22-deficient mice." (PMID 23853597, 2013). "IL-22-deficient mice were susceptible to C. albicans in the early but not late stages of infection, as indicated by signs of vaginal epithelial damage and inflammation, robust PMN recruitment, high S100a8 and S100a9 gene expression, calprotectin levels and fungal growth at 3 dpi." (PMID 23853597, 2013). "Whether IL-22 contributes to control TB at the site of infection is unknown." (PMID 22359547, 2012). "However, in this mouse model, IL-17A and IL-22 could be detected above uninfected controls only by 6 days after infection." (PMID 22675469, 2012). "Data were complemented by immunohistochemical detection of IL-22 in skin biopsies obtained from erythema chronicum migrans patients, though this pathological status may barely reflect innate skin immunoactivation in the initial phase of infection." (PMID 20976193, 2010). "We found that L. murinus and its derivative ICA can directly target Rorγt to promote ILC3s secretion of IL‐22, ameliorating intestinal barrier damage and thereby reducing TPN‐induced infection." (PMID 40236767, 2025). "This interaction is essential in infections, such as tuberculosis, where ILC3-driven IL-22 promotes early lung immunity and the formation of inducible bronchus-associated lymphoid tissue (iBALT)." (PMID 40872304, 2025). "After infection with PEDV for 48 h, the mRNA levels and protein levels of IL22 and pBD1 were both notably downregulated, while the mRNA level of miR-193a-5P was significantly decreased." (PMID 41262886, 2025). "The qPCR analysis revealed significant upregulation of IL-6, IL-17A, IL-22, IFN-β, IFN-γ, and TNF-α in duodenal epithelial cells following IBV CSL strain infection." (PMID 40871421, 2025). "Next, we determined differences in FD4 permeability between vehicle and recombinant IL-22 treated Ptpn2fl/fl and Ptpn2∆IEC mice post mAIEC infection." (PMID 40955058, 2025). "Recent data indicate the involvement of interleukin (IL)-17 and IL-22 in COPD pathophysiology — two cytokines crucial for regulating lung inflammation and infection." (PMID 41409289, 2025). "To further prove the impact of Aq in mitigating the consequences of WSSV infection, we next measured the levels of IL-22 production, otherwise known as one of the responders to WSSV infection in shrimp." (PMID 39857423, 2025). "We observed IL-22 induction from CD4+ T cell responses to both spike and non-spike antigens in children and to spike antigens in adults during the acute phase of infection." (PMID 40906527, 2025). "To determine the influence of coexistent Ss infection on type 1, type 17, and proinflammatory cytokines in TBI, we measured the QFT supernatants levels of IFN-γ, TNF-α, IL-2, IL-17, IL-22, IL-1α and IL-1β in TBI+Hel+ and TBI+Hel- individuals." (PMID 41583474, 2025).
infection (continued). "We chose to examine Ire1αΔRorc mice in the acute phases of infection by either Clostridium difficile or Citrobacter rodentium, since ILC3-derived IL-22 is essential to preserve epithelial barrier function, while CD4+ T cells are dispensable at this stage." (PMID 38722686, 2024). "IL-22-producing CD4+ T cells and ILC3 also play a crucial role in host defenses in the early phases of infection." (PMID 38799550, 2024). "IL-17A, IL-22, and IFN-γ are tissue-signalling cytokines that play important roles in inflammation and infection." (PMID 39695888, 2024). "Compared with the normal group, the expression of IL-17 and IL-22 increased first and then decreased after RSV infection, peaking in the lung on the third day after infection and in the small intestine and colon on the second day after infection (P < 0.01)." (PMID 38727214, 2024). "After infection with influenza A virus (IAV), IL-22 levels in the lung tissues of patients are significantly increased and can gradually return to normal as the disease improves." (PMID 36839448, 2023). "infection was significantly higher than those in PBS group (p<0.01), while the levels of GM-CSF and IL-22 were lower compared with those in PBS group." (PMID 36743311, 2023). "As a control, we also used SC5314-infected immunocompetent C57BL/6 mice, which displayed robust increases in the IL-22 and IFN-γ RNA levels that peaked on day 5 after SC5314 infection." (PMID 38298919, 2023). "After infection with Citrobacter, the expression of STAT3 in ILC3s is enhanced and binds with IL-22 to exert anti-infective effects." (PMID 37304260, 2023). "As infection progressed from ATB to relapse, Th cells producing IL-22 decreased (blue arc legend), while polyfunctional groups that include IL-17 increased (green arc legend groups)." (PMID 37898618, 2023). "A reduction in Krt5+ BC hyperplasia was observed in IL-22 LOF mice compared to WT control mice at all time points examined, which reached statistical significance by the day 17 post-infection time point." (PMID 37726288, 2023). "Quantification of the expression of six inflammatory markers (IL-5, IL-8, IL-22, CCL20, TIMP1, CSF2) was carried out at 2, 24, and 48 hr post-infection." (PMID 37218575, 2023). "Significant induction of type 17-related cytokines, including IL-17a and IL-22, was observed in lung tissue homogenates and/or bronchoalveolar lavage (BAL) of mice between days 5–11 after PR8 infection." (PMID 37726288, 2023). "To investigate the contribution made by IL-22 in the regulation of BC fate after PR8 infection, we used IL-22Cre/Cre (IL-22 LOF) and IL-22ra1fl/fl/Shh-Cre (IL-22r cLOF) mice to modulate IL-22 levels and signaling, respectively." (PMID 37726288, 2023). "Compared with the control group, the treatment with IL-22 highly inhibited the propagation of DHAV-1 and reduced the infection by 64.8%." (PMID 37391858, 2023). "The results of the present study showed that the expression of IL-22 increased the most in liver tissue among all tested organs; in addition, the highest expression of IL-22 after DHAV-1 infection was also observed in the liver." (PMID 37391858, 2023). "Ki67+ crypts, more distributed in the TA compartments, were significantly reduced in Il-22−/− and Il-18−/− mice at the steady state or during AIEC infection." (PMID 35169117, 2022). "By immunofluorescence analysis of littermate mice, we also found that Olfm4+ crypt base columnar (CBC) stem cells are greatly reduced in both Il-22−/− and Il-18−/− crypts at the steady state or during AIEC infection 26,35." (PMID 35169117, 2022). "A strong interaction between dietary APS and NE infection was observed in relation to IFN-γ, IL-17F and IL-22 (P < 0.05) in ileum." (PMID 35265068, 2022). "IL-22, secreted by CD3+ T cells and ILC3s in the intestine, has been shown to protect the host from infection as a downstream gene of the AhR pathway." (PMID 36439215, 2022).
infection (continued). "Collectively, these data indicate that Irf1-deficiency in the hematopoietic compartment is associated with a reduced capacity of intestinal lymphocytes to produce IL-22 and IFN-γ upon infection or IL-23 challenge." (PMID 36175404, 2022). "We conclude that in vivo maintenance of Ki67+ crypt regeneration and Paneth cells requires IL-22-Stat3 signalling and AIEC infection triggers an epithelial IL-22-Stat3-mediated Paneth cell response." (PMID 35169117, 2022). "Strikingly, infection with S. tm. induced in eSPF+SFB mice compared to SPF mice significantly increases the frequencies and numbers of IL-17A-IL-22+ and IL-17A+IL-22+ CD4+ T cells specifically in the cecal LPLs." (PMID 34566952, 2021). "IL-6, IL-23, and TGF-β and were seen in reduced levels at least in one post-infection period after L-Kyn and CH223191 treatments and this was accompanied by reduced levels of IL-17 (week 2) and IL-22 (both infection periods)." (PMID 33936043, 2021). "In this context, we recently reported a defective production of IL-22 in response to bacteria both in COPD patients and mice chronically exposed to CS, whereas IL-17 production is only altered after infection by S. pneumoniae." (PMID 33784296, 2021). "In this study, CXCL10, IL-2, IL-10, IL-22, MMP-9, and Fas-ligand were identified as discriminatory biomarkers for type I and type II infections." (PMID 34263738, 2021). "Infection with NTHi increased the production of IFN-γ, IL-17, and IL-22 in Air-mice as compared with PBS mice at 24h p.i.." (PMID 33784296, 2021). "Compared to WT animals, lungs of Il22−/− mice exhibited reduced gene and protein expression of NOS2 at 7 and 14 days after infection (respectively)." (PMID 32517114, 2020). "Our results show that the relative transcription levels of IL-17A, IL-22, IL-6, IL-1β, IFN-γ, and TNF-α increased at 5 and 12 days post H9N2 AIV infection, and these results are consistent with our previous research results and other reports." (PMID 33294434, 2020). "As expected, mice infected with Cr had increased colonic tissue expression of several cytokines associated with a pro-inflammatory Th1/Th17 immune response including IL-17A, IL-22, IL-6, IL-1β, TNF-α, and IFN-γ on day 12 after infection." (PMID 33076301, 2020). "Other studies indicate that IL-22 and IL-17, two highly related cytokines are both increased and necessary for S. aureus control in SSTI infection." (PMID 32637365, 2020). "As such ILC3 were reported to be a critical source of protective IL-22 early during infection with Citrobacter rodentium, and depletion of CD4+ CCR6+ ILC3 using an anti-CD4 antibody led to diminished IL-22 production and enhanced bacterial tissue infiltration." (PMID 33603753, 2020). "IL-22 and IFN-λ are both important cytokines that function at mucosal barriers in response to apparent infection." (PMID 32637365, 2020). "Infection with BCG was shown to exert a detrimental effect primarily upon epithelial cells, with corresponding increases in IL8, TNFα, IL22 and IL17a cytokine release, quantified by ELISA." (PMID 33116165, 2020). "The lung homogenates of WT and AhR−/− mice were collected after 96 h, 2 and 10 weeks of infection and used to evaluate the presence of cytokines (IL-12, TNF-α, IL-1β, IL-6, IL-23, IL-2, IFN-γ, IL-4, IL-17, IL-22, TGF-β, IL-10, IL-27, and IL-35)." (PMID 32647342, 2020). "Upon infection, CX3CR1+ DCs release the chemokine CXCL16, which activates ILC3 via CXCR6, thus stimulating IL-22 release and the expression of antimicrobial peptides (AMPs)." (PMID 32887435, 2020). "Previous studies showed that IL-22 induces Th1 signature cytokines such as IL-18 and IFN-γ during Toxoplasma gondii experimental infection." (PMID 32517114, 2020). "Whereas, primary infection with S. flexneri induces differentiation of CD4+ cells to Th17 cells that produce IL-17A and IL-22, secondary infection also produces Th1 cells that secrete IFN-γ." (PMID 30800131, 2019).
infection (continued). "The number of IL-22 secreting ILC3 cells in the whole colon were higher in D+ than D- mice at d0 and d10 post-infection." (PMID 30723466, 2019). "Overall, lower expression of IL17, IL22, PTX3, and heterophil attracting cytokines, such as CXCL8 and VCAM1 in our data suggests a dampened innate immune response post APEC O2-GFP infection." (PMID 31998322, 2019). "Infection of IL-10−/− mice with C. jejuni is characterized by increased levels of pro-inflammatory cytokines (TNF-α, IL-1β, IL-6, IFN-γ and IL-22) and infiltration of inflammatory cells in the colon." (PMID 31427597, 2019). "Other important findings described below (see lung models of infection) are that PIV can cleave surfactant proteins A and D and cytokine IL-22, a cytokine able to provide protection for the lung." (PMID 31443433, 2019). "At an early stage of the infection (4 DPI), ILC3 are the major source of IL-22 whereas CD4+ T cells secrete IL-22 at a later stage (after 9 DPI)." (PMID 30365535, 2018). "Unlike previous studies with Helicobacter pylori where infection causes adenocarcinoma and produces high levels of IL-17 and IL-21, only moderate increase in signature cytokines secreted by Th17 cells, such as IL-17, IL-17F, IL-21, and IL-22, was observed in our experiments." (PMID 29445365, 2018). "Compared to Mock infection, strain SE2472 infection strongly increased the mRNA levels of inflammatory cytokines including IFN-γ, IL-1β, MIP-2, IL-33, IL-17, IL-22, TNFα, etc.." (PMID 29208934, 2017). "Analysis of cytokines production by spleen and MLN cells in mice model have shown the production of IL-4, IL-10, IL-13, IL-17, IL-22, TNF-α, and IFN-γ after infection with both WB and GS strains." (PMID 28979269, 2017). "Our data suggest that, strong IFNG/IL22 responses, probably related to Th1 and NK cell involvement, is important for clearance of C. trachomatis and that the residual pro-inflammatory and pro-fibrotic phenotype that persists after infection might contribute to pathological scarring." (PMID 28966918, 2017). "At late stage of infection, PFOS exhibited more pro-inflammatory effect indicated by increased IL-17, IL-22 and IFN-γ by innate cells and enhanced Th17 cell immunity." (PMID 28701769, 2017). "We found at early phase of the infection, PFOS inhibited the expansion of the pathogen by promoting IL-22 production from the group 3 innate lymphoid cell (ILC3) in an aryl hydrocarbon receptor dependent manner." (PMID 28701769, 2017). "Confirming these data, prophylactic administration of IL-22 correlated with a decrease in CXCL2 levels and PMN accumulation during infection." (PMID 28887540, 2017). "This early mucosal resistance phenotype was associated with an early increase of mucosal protein levels of IL-1β, IL-22, KC/CXCL1 and MCP-1 and elevated transcription rates of Cxcl1 and Nos2/iNos measured at 18 hours post infection." (PMID 28662171, 2017). "Inflammatory cell infiltration into the liver and the heart observed on day 14 post infection was similar in C57BL/6 and IL-22−/− mice." (PMID 27650379, 2016). "During early infection (2wk), expression of pro-inflammatory cytokines IFN-γ, TNF-α, IL-17, IL-18, IL-22 (Th1 and Th17 responses) was negatively correlated with ANXA1 expression." (PMID 27484833, 2016). "We also quantified the levels of intestinal IL-17 and IL-22 producing cells, and here ART’s reconstitution was minimal, with all three subsets’ levels remaining significantly lower p<0.001) than pre-infection levels." (PMID 26829644, 2016). "We here show that after infection of C57BL/6 mice with Mtb, IL-22 expression is in fact dependent on IL-23." (PMID 23460846, 2013). "During the course of low dose infection, both, C57BL/6 and IL-22−/− mice generated similar frequencies of Mtb-specific TH1 and TH17 cells within the CD4+ cell population and within total lung cell suspensions." (PMID 23460846, 2013).